FXYD6 (FXYD domain containing ion transport regulator 6)
Diseases named in the same sentence as FXYD6 in open-access papers (continued):
Sharing a sentence is not in itself a finding about the gene and the disease.
cancer (11 papers, 2014 to 2025). A tumor composed of atypical neoplastic, often pleomorphic cells that invade other tissues. "FXYD6 may be a new biomarker for cancer and may be associated with a favorable prognosis in this malignant disease." (PMID 34150649, 2021). "FXYD6 is widely distributed in different tissues and organs, and related to different cancers, such as hepatocellular carcinoma, pancreatic cancer, and cholangiocarcinoma." (PMID 38093622, 2023). "As a member of classical and critical NKA regulator FXYD family, changes of FXYD6 expression were also found to be related to the progression of various cancers." (PMID 38093622, 2023). "The positive expression rate of FXYD6 in poorly-differentiated carcinoma was significantly lower compared to well- and moderately-differentiated carcinoma (87.5 vs. 40%; P=0.000)." (PMID 24396454, 2014). "In the first step, we used RT-PCR to identify alterations in FXYD6 expression in carcinoma tissues." (PMID 40170843, 2025). "FXYD1, FXYD3, FXYD6 and FXYD7 were significantly downregulated in cancer samples, while FXYD4 and FXYD5 were markedly overexpressed." (PMID 34270462, 2021).
tumor (11 papers, 2014 to 2025). "Excessive expression of FXYD6 would cause the inactivation of the Na+/K+-ATPase to reduce the production of ATP in tumor cells." (PMID 40170843, 2025). "To determine the mechanism underlying FXYD6-induced tumor cell migration and proliferation, we measured the phosphorylation of both kinases when FXYD6 expression levels were modulated." (PMID 24715268, 2014). "Furthermore, FXYD6 expression was also observed to be associated with tumor differentiation." (PMID 24396454, 2014). "We retrieved from the core genes and combined them with the correlation of previous clinical data and found that FXYD6 plays an important role in tumor metabolism and the electron transport respiratory chain." (PMID 40170843, 2025). "FXYD6, being a crucial differential molecule between subtypes, exerts a tumor-promoting effect when knocked down; conversely, its overexpression yields an opposite outcome." (PMID 40170843, 2025). "FXYD6 biological functions were explored through enrichment analysis, and tumor immune infiltration was assessed using ESTIMATE and TIMER algorithms." (PMID 38093622, 2023). "In summary, FXYD6 protein was highly expressed in HCC and associated with MVI,pathological stage, and early recurrence of the tumor." (PMID 33817214, 2020). "Among these genes, PLP2 was upregulated and positively associated poorer survival, whereas LYVE1, FABP4, TGFBR3, and FXYD6 were downregulated and identified as tumor suppressor genes." (PMID 31803141, 2019). "To determine the role of FXYD6 in tumor progression, we firstly generated a panel of mouse mAbs (monoclonal antibody)." (PMID 24715268, 2014). "The expression levels of FXYD6 in CC were observed to correlate with the degree of differentiation of the tumor." (PMID 24396454, 2014). "Taken together, these results show that our self-generated FD10 can be used in further investigation of the FXYD6’s role in tumor progression." (PMID 24715268, 2014). "Consistent with previous studies, excessive expression of FXYD6 could inhibit the growth of tumor cells, and this phenomenon might be related to its function." (PMID 40170843, 2025). "Whether FXYD6 exerts a tumor suppressor role in these tumors and its molecular mechanisms deserves further study." (PMID 31803141, 2019). "Importantly, blockade of FXYD6 by our self-generated anti-FXYD6 functional antibody significantly inhibited xenografted tumor growth, suggesting that FXYD6 is a novel therapeutic target toward HCC." (PMID 24715268, 2014). "The significant differences in FXYD6 expression in normal bile duct and CC tissues indicate that this protein may play an important role in carcinogenesis, for example tumor initiation." (PMID 24396454, 2014). "To assess whether FXYD6 was involved in the tumor formation and growth in vivo, we established xenografted HCC models in nude mice using the stable transfectants of SMMC7721-mock and SMMC7721-FXYD6 cells." (PMID 24715268, 2014). "Inspired by the close correlation between FXYD3/FXYD5 and tumor progression, we supposed that FXYD6 may be also involved in tumor malignancy." (PMID 24715268, 2014). "In-depth analysis of the DEGs that exhibited significant changes in K562 cells treated with WIP2W showed an elevation of tumor suppressor genes, including OSCP1, and genes related to cell apoptosis such as FXYD6, NPTX1, and GPR142." (PMID 37765274, 2023). "The potential tumor-suppressing role of CLCNKB, FBXO27, and FXYD6 in PTC requires further validation." (PMID 33553144, 2020). "Thus, FXYD6 promoting tumor growth suggests FXYD6 may be a therapeutic target for HCC." (PMID 24715268, 2014). "Analysis of the TIMER database demonstrated that FXYD1, FXYD6 and FXYD7 had significantly negative associations with tumor purity, while these genes had markedly positive correlations with CD4+ T cells, macrophages and dendritic cells." (PMID 34270462, 2021).
tumor (continued). "Furthermore, we have found that overexpression of FXYD6 increases migration and proliferation in the human SMMC7721 cells, which agrees with the role of FXYD3 or FXYD5 overexpression in tumor progression." (PMID 24715268, 2014). "However, whether or not FXYD6 is up-regulated and involved in tumor progression, particularly in HCC, remains elusive." (PMID 24715268, 2014).
FXYD6 also shares sentences with these, for which no sentence is quoted: adenocarcinoma (1 paper); adrenocortical carcinoma (1); Alzheimer disease (1); Astrocytoma (1); bladder urothelial carcinoma (1); breast carcinoma (1); breast invasive carcinoma (1); cervical cancer (1); CNS tumor (1); colitis (1); colon carcinoma (1); heart failure (1); Hypomagnesemia (1); liver fibrosis (1); lymph node metastasis (1); metabolic disorders (1); neurodegenerative disease (1); prostate carcinoma (1); renal cell carcinoma (1); thyroid carcinoma (1).